SOX9 (SRY-box transcription factor 9)
Diseases named in the same sentence as SOX9 in open-access papers (continued):
Sharing a sentence is not in itself a finding about the gene and the disease.
glioma (59 papers, 2013 to 2025). A benign or malignant brain and spinal cord tumor that arises from glial cells (astrocytes, oligodendrocytes, ependymal cells). "SOX9, a transcription factor critical for stem cell maintenance and plasticity, has also been implicated in glioma progression." (PMID 40159622, 2025). "The outcomes revealed that high expression of SOX9 was associated with significantly shorter overall survival and disease-free survival times in TCGA glioma patients." (PMID 37291545, 2023). "The receiver operating characteristic (ROC) curve revealed that the diagnostic sensitivity of ANRIL combined with SOX9 for glioma was 81.62%, and the specificity was 90.83% (P<0.01)." (PMID 34556140, 2021). "SOX9 has abnormal expression in many tumors including glioma, but the underlying molecular mechanism is unclear." (PMID 34556140, 2021). "lncRNA-CDKN2B antisense RNA 1 (ANRIL) and SRY-box transcription factor 9 (SOX9) has abnormal expression in many tumors including glioma, but the underlying molecular mechanism is unclear." (PMID 34556140, 2021). "Sox9 is a critical regulatory target of TGF-β since its overexpression rescued the malignant phenotypes of glioma cells caused by inhibition of TGF-β signaling." (PMID 33613515, 2020). "In GBM, SOX9 protein expression suppressing in the glioma cell lines was reported displayed loss of cell adhesion, inhibition of AKT phosphorylation and G1 arrest." (PMID 29416606, 2018). "In current study, we confirmed that SOX9 rs1042667 was significantly associated with increased gliomas risk (Allele C vs A: OR=1.25; 95% CI=1.11-1.40; P=1.2×10−4)." (PMID 27589569, 2016). "Results strongly indicated that SOX9 rs1042667 was significant associated with 1.25-flod increased gliomas risk, after adjusted by age, gender, family history of cancer, smoking status and alcohol status." (PMID 27589569, 2016). "Results showed that SOX9 rs1042667 was significant associated with increased gliomas risk after adjusted by age, gender, family history of cancer, smoking status and alcohol status (Allele C vs A: OR=1.25; 95% CI=1.11-1.40; P=1.2×10−4)." (PMID 27589569, 2016). "This should be the first genetic association study which aims to evaluated the association between genetic variants of SOX9 and susceptibility of gliomas." (PMID 27589569, 2016). "Our results indicated that SOX9 rs1042667 was significant associated with increased gliomas risk (Allele C vs A: OR=1.26; 95% CI=1.04–1.54; P=0.019)." (PMID 27589569, 2016). "Conclusively, the present two-stage, case-control study revealed that SOX9 rs1042667 was associated with increased gliomas risk in a Chinese population." (PMID 27589569, 2016). "when merged two stages together, SOX9 rs1042667 was significant associated with increased gliomas risk (Allele C vs A: OR=1.25; 95% CI=1.11-1.40; P=1.2×10−4)." (PMID 27589569, 2016). "The results showed that SOX9 rs1042667 was also significant associated with increased gliomas risk (Allele C vs A: OR=1.24; 95% CI=1.08-1.42; P=0.002)." (PMID 27589569, 2016). "Previous studies showed that high levels of SOX9 are associated with poor glioma patient survival." (PMID 35562901, 2022). "The mechanisms underlying Sox9 regulation by TGF-β pathway in glioma cells were probed." (PMID 33613515, 2020). "In current study, we systematically evaluated whether genetic variants of SOX9 contribute to susceptibility of gliomas among Chinese population using a two-stage, case–control study." (PMID 27589569, 2016). "Among them, SOX9, which acts as a transcription factor that plays a central role in the development and differentiation of multiple cell lineages, were suggested to be associated with risk and prognosis of gliomas." (PMID 27589569, 2016). "Interestingly, in glioma cell lines, Sox9 knockdown by siRNA reduced cell proliferation, implying a certain causal relationship between Sox9 expression and tumor growth." (PMID 25955804, 2015).
glioma (continued). "In current study, we systematically evaluated whether genetic variants of SOX9 gene, a transcription factor that plays a central role in the development and differentiation of tumors, contribute to susceptibility of gliomas among Chinese population using a two-stage, case–control study." (PMID 27589569, 2016). "Functional analyses have demonstrated that SOX9 plays a key role in sustaining glioma stemness, further reinforcing its significance in tumour progression." (PMID 40159622, 2025). "MiR-30 has been identified as a tumor suppressor in glioma, as overexpression of miR-30 leads to suppression of proliferation, migration, and invasion of glioma cells by regulating the expression of SOX9." (PMID 39805813, 2025). "In this study, we identified a member of the DUB family, USP18, which regulates the protein stability of SOX9, thereby promoting the maintenance of glioma stemness and tumour progression." (PMID 40374599, 2025). "To further investigate the impact of USP18/SOX9 on glioma progression, we established orthotopic xenograft models." (PMID 40374599, 2025). "To further validate the clinical relevance of this regulation, we analyzed SOX9 protein expression by immunohistochemistry in 90 human glioma specimens and correlated its expression with USP18 IHC scores." (PMID 40374599, 2025). "Immunofluorescence experiments further confirmed the colocalization of the USP18 protein and the SOX9 protein in glioma cells." (PMID 40374599, 2025). "The angiotensin II type 1 receptor/CXCR4/NF-κB signaling pathway is involved in glioma progression, and SOX9 is the downstream target of telmisartan." (PMID 39063232, 2024). "They found that the upregulation of Sox9 due to TGF-β signaling was correlated with poor clinical prognosis in patients with glioma." (PMID 38926762, 2024). "26,27 Other notable transcriptional differences in EGFRvIII-containing samples include increased HDAC6 expression, reported to promote glioma proliferation; increased expression of the stem cell marker SOX9; and increased expression of tumor suppressor TSC2." (PMID 38665799, 2024). "In patients with glioma, a higher level of SOX9 expression is correlated with an unfavorable prognosis." (PMID 37183261, 2023). "Functional analyses also revealed a strong inverse correlation between the expression of PR-LncRNAs and SOX family members (SOX1, SOX2, and SOX9) in glioma clinical biopsies and glioma cells." (PMID 37047365, 2023). "TCGA database analysis showed that SOX9 is positively related to Hif1α, a hypoxia-related protein, in glioma." (PMID 36810326, 2023). "On the other hand, rapamycin attenuated the production of SOX protein, and it was found that combining rapamycin and temozolomide suppressed the progression of glioma in cells that expressed high levels of SOX2/SOX9." (PMID 37183261, 2023). "More recent data indicate that SOX9 expression in glioma tissues was significantly higher compared to corresponding non-neoplastic brain tissues and associated with poor clinical outcomes of patients." (PMID 37047365, 2023). "We first characterized the expression of SOX9 in glioma grade taking advantage of publicly available TCGA and Rembrandt cohorts." (PMID 35562901, 2022). "Analysis of glioma clinical biopsies confirmed a positive correlation between SOX9/STAT3/PML and poor patient survival among the cases with the highest SOX9 expression levels." (PMID 35562901, 2022). "After transfecting glioma cell lines with ANRIL and SOX9 inhibitory sequences, we measured apoptosis-related proteins (bcl-2 and bax) to observe changes in multiplication, invasion, and apoptosis in glioma cell lines." (PMID 34556140, 2021). "Here we employed qRT-PCR to determine serum lncRNA-ANRIL and SOX9 levels in glioma patients and healthy adults and detected abnormally upregulated expression of the two in the serum of glioma patients." (PMID 34556140, 2021).
glioma (continued). "The present study investigated lncRNA-ANRIL and SOX9 levels in gliomas and their effects on the biological functions of cells, aiming to enlighten new ways of diagnosis and treatment for gliomas in terms of molecular biology." (PMID 34556140, 2021). "We further analyzed patients’ clinicopathological characteristics and found that high-lncRNA-ANRIL and SOX9 levels were correlated with tumor grade, tumor diameter, distant metastasis, and family history of glioma." (PMID 34556140, 2021). "ANRIL and SOX9 were closely related to tumor grade, tumor diameter, distant metastasis, and family history of glioma (P<0.01)." (PMID 34556140, 2021). "Here we first tested the expression of lncRNA-ANRIL and SOX9 in normal adults and glioma patients to analyze the effects of the two genes on the prognosis of glioma patients." (PMID 34556140, 2021). "This study set out to investigate the serum lncRNA-ANRIL and SOX9 levels in glioma patients and their effects on prognosis." (PMID 34556140, 2021). "Using the quantitative real-time polymerase chain reaction (qRT-PCR), lncRNA-ANRIL and SOX9 were measured to explore their values in the early diagnosis of glioma." (PMID 34556140, 2021). "For example, the limited experimental conditions hindered us to figure out the specific regulatory network of lncRNA-ANRIL and SOX9 to affect glioma." (PMID 34556140, 2021). "ANRIL and SOX9 were markedly higher in glioma cell lines (U251 and U87) than in normal brain cells (P<0.01)." (PMID 34556140, 2021). "The testing of biological behaviors revealed that lncRNA-ANRIL and SOX9 worked as tumor-promoting genes in glioma." (PMID 34556140, 2021). "Further study in glioma cells revealed that TGF-β signaling reduces the proteasomal degradation of Sox9." (PMID 33613515, 2020). "LINC00174 knockdown improves the response of human glioma cells to temozolomide by modulating the miR-138-5p/SOX9 axis." (PMID 33080570, 2020). "From the genes selected, known markers in glioma and GBM, namely SOX9 and EGFR, are here associated to astrocyte development and differentiation." (PMID 32070274, 2020). "We established that Sox9 overexpression underlies glioma pathogenesis, and TGF-β pathway plays an essential role in upregulating Sox9 and thereby promoting glioma progression." (PMID 33613515, 2020). "Here, we found that the Sry-related high mobility group box (Sox) family transcription factor, Sox9, was upregulated and correlated with poor prognosis of clinical gliomas." (PMID 33613515, 2020). "We next investigated the oncogenic signal pathways responsible for Sox9 upregulation in glioma cells." (PMID 33613515, 2020). "Sox9 downregulation also inhibited the development of xenograft tumors in nude mice challenged with the U87 glioma cells." (PMID 33613515, 2020). "We found here that Sox9, a transcription factor commonly overexpressed in various glioma and glioblastoma, is upregulated by TGF-β signaling." (PMID 33613515, 2020). "Consistent with its critical role in glial differentiation, Sox9 deregulation is closely related to the occurrence and development of glioma." (PMID 33613515, 2020). "In the present study, we investigated the role of Sox9 in regulation of the malignant phenotypes of glioma cells, and explored upstream pathways responsible for Sox9 deregulation." (PMID 33613515, 2020). "Immunohistochemical staining and western blot of five patients showed that Sox9 was upregulated in glioma tissues when compared with the peritumor tissues." (PMID 33613515, 2020). "We found here that Sox9 was overexpressed in clinical gliomas, and correlated with a poor prognosis of glioma patients." (PMID 33613515, 2020). "Increasing evidence has suggested that Sox9, an indispensable transcription factor in the development of the nervous system, plays a pivotal role in the pathogenesis of glioma." (PMID 33613515, 2020). "The expression of Sox9 was positive correlated with TGF-β1 via the analysis of TGF-β1 and Sox9 in IHC of glioma tissues." (PMID 33613515, 2020).
glioma (continued). "We and others have demonstrated previously that Sox9, which is upregulated via various mechanisms, contributes to the occurrence and progression of glioma." (PMID 33613515, 2020). "Sox9 promotes migration and invasion of glioma cells and in vivo development of xenograft tumors from inoculated glioma cells." (PMID 33613515, 2020). "Increasing expression of circPTN rescued the inhibition of proliferation and downregulation of SOX9/ITGA5 in glioma cells by miR-145-5p/miR-330-5p." (PMID 31511040, 2019). "Mechanistically, we found an inverse correlation between PR-LncRNA expression and SOX1, SOX2 and SOX9 stem cell factors in human glioma biopsies and in glioma cells in vitro." (PMID 30143669, 2018). "Knockdown of SOX9 in GBM cell lines markedly suppressed the stem cell-like properties, including stem cell marker expression level and glioma cell sphere formation, indicating that SOX9 was essential for GSC self-renewal." (PMID 29416606, 2018). "Given that the SOX9 was involved in glioma stem cell-like properties, we were interested in the relevant downstream genes regulated by SOX9 in glioma." (PMID 29416606, 2018). "Previously, we have observed that silencing of SOX9 suppressed glioma cells proliferation both in vitro and in vivo." (PMID 29416606, 2018). "The sphere-forming units (SFU) and diameter of spheres were detected to access the effect of SOX9 knockdown on glioma sphere formation." (PMID 29416606, 2018). "Silencing of SOX9 down-regulated a broad range of stem cell markers and inhibited glioma cell colony and sphere formation." (PMID 29416606, 2018). "In this paper, SOX9 was demonstrated to be a key regulator in glioma tumorigenesis and GSC self-renewal." (PMID 29416606, 2018). "To determine the biological function of SOX9 in glioma stemness, we applied shRNAs against SOX9 to U251 and U87MG cells, and found that SOX9-shRNAs significantly decreased SOX9 protein expression in U251 and U87MG cells." (PMID 29416606, 2018). "Glioma-associated DEGs CD244, IL21, RET, TGFA were up-regulated and AQP9, IGFBP2, EGFR, SOX9 were down-regulated specifically in the rat." (PMID 29352201, 2018). "Our data suggested that miR-101 regulated glioma cells proliferation and invasion both in vitro and in vivo by directly targeted SOX9." (PMID 27911279, 2017). "MTT assay, wound healing assays and trans-well assay were used to test the effect of SOX9 on glioma cells." (PMID 27911279, 2017). "This study suggests us that miR-101 and SOX9 are key regulators in human glioblastoma and provides new therapeutic targets for glioma therapy." (PMID 27911279, 2017). "The TargetScan Program suggested that the 3′UTR region of the SOX9 gene containing the binding sites of miR-101, and the expression level of SOX9 in glioma (II-III) tissue was higher than that of the normal brains tissue." (PMID 27911279, 2017). "To acknowledge the targeting relationship between SOX9 and miR-101 in GBM, we also studied the SOX9 function in glioma." (PMID 27911279, 2017). "Major TGF-Beta-EMT inducing factors (RHOA, RAC1, ROCK2, CDC43 and LIMK1) and EMT transcription factors (TWIST1, SOX9, TRIM28 and SERP2) have among the highest risk scores in our glioma transcriptional model." (PMID 28916782, 2017). "Silencing of SOX9 exerted similar effects with miR-101 overexpression on glioma cells proliferation and invasion." (PMID 27911279, 2017). "Given the biological importance of SOX9 gene and its implication in gliomas, we performed the current two-stage, case–control study to investigated the association between tag SNPs in the SOX9 gene and gliomas susceptibility among Chinese population." (PMID 27589569, 2016). "Overall, our findings provided evidence for the important role of SOX9 gene in the tumorigenesis of gliomas." (PMID 27589569, 2016).
glioma (continued). "Further functional and genetic association studies in larger population, with different ethnic groups included, are warranted to further validate our results and explore the possible mechanism of SOX9 gene in the carcinogenesis and development of gliomas." (PMID 27589569, 2016). "To confirm whether SOX9 mediates the biological functions of USP18 in glioma cells, we conducted a series of rescue experiments." (PMID 40374599, 2025). "Therefore, proteins associated with glioma stemness are more likely to be targeted and regulated by USP18, especially SOX9, because of its widely recognised role in promoting GSCs." (PMID 40374599, 2025). "SOX9 and HEY2, TFs associated with glioma stemness, were highly expressed in the Glioma-SPARCL1 population, suggesting that this population might consist of glioma stem cells." (PMID 38515213, 2024). "This allows Sox9 to function unchecked, leading to increased invasiveness of glioma cells." (PMID 38926762, 2024). "Furthermore, serum levels of SOX9 and lncRNA-ANRIL (Antisense Non-coding RNA in the INK4 Locus) were higher in patients with glioma than in healthy people and were strongly associated with unfavorable prognosis." (PMID 37047365, 2023). "Telmisartan dose-dependently inhibited SOX9 expression in glioma cells." (PMID 37291545, 2023). "Moreover, SOX9 also plays a critical role in stemness maintenance in glioma stem cells (GSCs) because silencing SOX9 suppresses GSC proliferation." (PMID 37291545, 2023). "SOX9 knockdown impairs GSCs proliferation, confirming its potential as a target for glioma therapy." (PMID 35562901, 2022). "Interestingly, STAT3 knockdown in GSCs and conventional glioma cell lines coincided with the phenotypes described with SOX9 silencing of reduced self-renewing in vitro and decreased tumorigenic activity in vivo." (PMID 35562901, 2022). "In this study, we characterized the function of SOX9 directly in patient-derived glioma stem cells." (PMID 35562901, 2022). "In summary, lncRNA-ANRIL and SOX9 levels were higher in glioma patients than in healthy people." (PMID 34556140, 2021). "Knockdown of LINC00174 by regulating miR-138-5p/SOX9 axis could decrease chemoresistance to TMZ in glioma." (PMID 34178658, 2021). "We aimed to enlighten new ways to regulate glioma cell proliferation and invasion, to explore the possibility of lncRNA-ANRIL and SOX9 to act as new targets for glioma gene therapy, and to provide a reliable reference for future clinical research and diagnosis of gliomas." (PMID 34556140, 2021). "lncRNA-ANRIL and SOX9 levels were higher in glioma patients than in healthy people." (PMID 34556140, 2021). "Similarly, Sox9 knockdown significantly decreased the invasiveness of glioma cells in a Transwell assay." (PMID 33613515, 2020). "Sox9 knockdown resulted in significantly suppressed proliferation, migration, and invasion of glioma cells, as well as impaired in vivo tumor development in a xenograft model, suggesting that Sox9 facilitates the formation of primary tumors probably via improving local invasion." (PMID 33613515, 2020). "CCK8 assays indicated that Sox9 silencing resulted in a moderate growth inhibition of glioma cells." (PMID 33613515, 2020). "These founding demonstrated that SOX9 was essential for glioma cell stemness." (PMID 29416606, 2018). "In this study, we found that miR-101 could inhibit the proliferation and invasion of glioma cells both in vitro and in vivo by directly targeting SOX9 [sex-determining region Y (SRY)-box9 protein]." (PMID 27911279, 2017). "On the contrary, MKP1 levels were reduced in glioma cells with elevated SOX2 or SOX9 activity." (PMID 29284798, 2017). "Results also showed that SOX9 was essential for glioma tumorigenesis both in vitro and in vivo." (PMID 27911279, 2017). "Furthermore, SOX9 silencing also markedly inhibited mice xenograft tumor growth, indicating that SOX9 was essential for glioma cell proliferation both in vitro and in vivo." (PMID 27911279, 2017).